GATAD2B (GATA zinc finger domain containing 2B)
Description:
Transcriptional repressor. Acts as a component of the histone deacetylase NuRD complex which participates in the remodeling of chromatin. Enhances MBD2-mediated repression. Efficient repression requires the presence of GATAD2A. Targets MBD3 to discrete loci in the nucleus. May play a role in synapse development.
Synonyms: P66beta; GANDS; MRD18; p68
Tractability: PROTAC: UniProt records ubiquitination sites on it; ubiquitination databases record sites on it; its protein half-life has been measured.
Gene: Protein-coding gene on chromosome 1 (153,789,030 to 153,923,360, reverse strand). Ensembl gene ENSG00000143614.
Subcellular location: Nucleus speckle; Nucleus; Chromosome
Subcellular location (Human Protein Atlas): Nucleoplasm
Pathways (Reactome):
Gene expression (Transcription): ERCC6 (CSB) and EHMT2 (G9a) positively regulate rRNA expression; RNA Polymerase I Transcription Initiation; Regulation of endogenous retroelements by KRAB-ZFP proteins; Regulation of endogenous retroelements by Piwi-interacting RNAs (piRNAs)
Chromatin organization: HDACs deacetylate histones; Interaction of NuRD complexes with transcription factors; NuRD complex assembly
Developmental Biology: Differentiation of naive CD4+ T cells to T helper 2 cells (Th2 cells); Transcriptional regulation of brown and beige adipocyte differentiation by EBF2
Disease: Potential therapeutics for SARS
Signal Transduction: Regulation of PTEN gene transcription
Gene Ontology:
Molecular function: nucleosomal DNA binding; protein binding; DNA-binding transcription factor activity, RNA polymerase II-specific; sequence-specific DNA binding; zinc ion binding
Biological process: chromatin remodeling; negative regulation of DNA-templated transcription; negative regulation of transcription by RNA polymerase II; positive regulation of DNA-templated transcription; regulation of cell fate specification; regulation of stem cell differentiation; regulation of DNA-templated transcription
Cellular component: chromatin; chromosome; chromosome, telomeric region; nuclear speck; nucleoplasm; nucleus; NuRD complex; protein-containing complex
Genetic constraint (gnomAD): Loss-of-function variants: 6 observed, 50.18 expected, observed/expected ratio (o/e) 0.12, 90% interval 0.064 to 0.24. The upper end of that interval is the gene's LOEUF score, 0.24, which puts it in group 1 of 6, group 1 being the genes least tolerant of losing a copy. Missense variants: 406 observed, 693.75 expected, observed/expected ratio (o/e) 0.59, 90% interval 0.54 to 0.63. Synonymous variants: 261 observed, 256.45 expected, observed/expected ratio (o/e) 1.02, 90% interval 0.92 to 1.13.
Gene-disease validity (ClinGen):
ClinGen rates the evidence that GATAD2B causes each of these diseases.
severe intellectual disability-poor language-strabismus-grimacing face-long fingers syndrome (autosomal dominant): Definitive. An autosomal dominant non-syndromic intellectual disability that has material basis in an autosomal dominant mutation of GATAD2B on chromosome 1q21.3.
Homologues: Orthologues: macaque GATAD2B (100% identical), chimpanzee GATAD2B (99% identical), pig GATAD2B (99% identical), guinea pig GATAD2B (99% identical), rabbit GATAD2B (99% identical), mouse Gatad2b (98% identical), rat Gatad2b (98% identical), dog GATAD2B (87% identical), tropical clawed frog gatad2b (78% identical), zebrafish gatad2b (74% identical), Drosophila melanogaster simj (33% identical), Caenorhabditis elegans dcp-66 (20% identical). Paralogues in human: GATAD2A (42% identical).
Diseases named in the same sentence as GATAD2B in open-access papers:
GATAD2B is named in the same sentence as 29 diseases in open-access papers, as found by Europe PMC text mining. Sharing a sentence is not in itself a finding about the gene and the disease. The quoted sentences say what the papers report.
Intellectual disability (9 papers, 2017 to 2025). "These mice also had abnormal cortical development and gene expression indicating the intellectual disability associated with GATAD2B mutations results from abnormal epigenetic transcriptional regulation of corticogenesis." (PMID 38238293, 2024). "Diseases associated with GATAD2B include mental retardation and severe intellectual disability with distinct facial features." (PMID 29147026, 2017). "Individuals with Kleefstra syndrome and GATAD2B‐related syndrome, which are both typically associated with moderate‐to‐severe intellectual disability, had lower adaptive profiles compared to the Koolen‐de Vries syndrome group (typically mild intellectual disability)." (PMID 39846212, 2025). "Cell cluster-specific Gatad2b dosage-sensitive genes include Frmd4a, associated with intellectual disability and Robo1 that mediates proliferation and neurogenesis in development and is clinically associated with a neurodevelopmental disorder in cluster 0 (Layer II-VI)." (PMID 38238293, 2024). "Mutations and deletions in Gatad2b have been associated with intellectual disabilities." (PMID 30210525, 2018). "GATAD2B (GATA zinc finger domain containing 2B) variants are associated with the neurodevelopmental syndrome GAND, characterized by intellectual disability (ID), infantile hypotonia, apraxia of speech, epilepsy, macrocephaly and distinct facial features." (PMID 38238293, 2024). "Recently, mutations in GATAD2B were identified in patients with GAND (GATAD2B-associated neurodevelopmental disorder), a NDD characterized by intellectual disability (ID), infantile hypotonia, apraxia of speech, epilepsy." (PMID 38238293, 2024). "Among genes with predicted probabilities greater than 0.90 (ranks 1–55), four genes (WDR45, CLTC, BRPF1, and GATAD2B) do not possess SFARI annotations, but have been associated with neurodegeneration and intellectual disability according to OMIM annotations." (PMID 35596027, 2023).
lung carcinoma (4 papers, 2018 to 2025). "The Nanoluc-tagged GATAD2B, serving as BRETn donor, was scanned across 83 lung-cancer associated genes fused with Venus-tag45, serving as BRETn acceptor, in a multiple DNA titration combination fashion to generate BRETn saturation curve." (PMID 30013058, 2018). "This role of GATAD2B in CSCs aligns with the reported role of GATAD2B in promoting metastasis in KRAS-mutant lung cancer, strengthening the role of GATAD2B in cancer." (PMID 40136647, 2025). "To date, the role of GATAD2B in those NOTCH1-addicted cancers is unclear, although GATAD2B has been identified as a metastatic driver in lung cancer." (PMID 38043798, 2024). "We further show here that high GATAD2B expression correlates with worsened outcomes in lung cancer patients and cooperates with KRAS to promote gain-of-function pro-oncogenic and pro-metastatic transcriptional programs including MYC to mediate cell invasion in vitro and tumor progression in vivo." (PMID 30013058, 2018). "Survival analysis of 1145 lung cancer patients, indicated worse overall outcome for those whose tumors expressed high vs. low levels of GATAD2B (HR = 1.49, P < 2.6E-6, log rank test), a finding that was even more significant among patients with adenocarcinoma (HR = 1.78, P < 4.1e-06, log rank test)." (PMID 30013058, 2018). "In this study the authors perform an in vivo functional screening and identify GATAD2B as a driver of tumor growth and metastasis in KRAS-driven lung cancer." (PMID 30013058, 2018). "Mechanistic evaluation of one gene, GATAD2B, illuminates its role as a dual activity gene, promoting both pro-tumorigenic and pro-metastatic activities in KRAS-mutant lung cancer through interaction with c-MYC and hyperactivation of the c-MYC pathway." (PMID 30013058, 2018). "Among those genes, functional characterization of GATAD2B illuminates its role as a potent driver of tumor growth and metastasis in KRAS-driven lung cancers." (PMID 30013058, 2018).
developmental delay (3 papers, 2023 to 2026). "In Family 55, WES trio analysis identified a de novo synonymous variant in GATAD2B (NM_020699.4: c.288C > T, p.Gly96=) in a proband presenting with global developmental delay." (PMID 41523913, 2026). "Developmental disorders caused by mutations in GATAD2B (OMIM 615074), ADNP (OMIM 615873), BCOR (OMIM 300166) and NR2F1 (OMIM 615722) have features that overlap with those of TBR1-related disorder, including developmental delay, ID, speech and language impairments and autistic behaviors." (PMID 36579832, 2023).
Anxiety (2 papers, 2025). Intense feelings of nervousness, tension, or panic often arise in response to interpersonal stresses. "Nonetheless, co‐occurring conditions were also common across the other two groups: anxiety and ADHD in Koolen‐de Vries syndrome, and sleep problems, anxiety, and mood disorders in GATAD2B‐related syndrome." (PMID 39846212, 2025).
autism (1 paper, 2024). Persistent deficits in social interaction and communication and interaction as well as a markedly restricted repertoire of activity and interest as well as repetitive patterns of behavior. "Arpp21 and the autism gene Grin2b, that control dendritogenesis and branching were also Gatad2b dosage-sensitive genes differentially expressed in more than one cell cluster, with Grin2b being clinically associated with epilepsy and autism." (PMID 38238293, 2024).
breast carcinoma (1 paper, 2025). "Thus, GATAD2B levels are increased in aggressive breast cancer cells, can be regulated by O-GlcNAcylation and associate with poor survival in human breast cancer patients." (PMID 40136647, 2025). "Similarly, reducing O-GlcNAcylation on GATAD2B by mutating potential modification Serines to Alanines also shortens GATAD2B half-life and increases ubiquitination level of GATAD2B, subsequently impairs mammosphere formation of breast cancer cells." (PMID 40136647, 2025). "Similar results are seen in SUM159 cells overexpressing GATAD2B when compared to control cells, further confirming the potential role of GATAD2B in protecting breast cancer cells from chemotherapy." (PMID 40136647, 2025). "We stably overexpressed GATAD2B in breast cancer cells and assessed the cancer stem-like cells properties." (PMID 40136647, 2025). "Overexpression of GATAD2B increases the CSCs properties in breast cancer cells, but also promotes resistance to apoptosis induced by paclitaxel in vitro." (PMID 40136647, 2025). "Together, these data show a crucial role of ITCH in mediating GATAD2B levels and regulating CSCs in breast cancer." (PMID 40136647, 2025). "Increased expression of GATAD2B in breast cancer cells protects from paclitaxel-mediated apoptosis and clonogenic survival and requires O-GlcNAcylation of GATAD2B." (PMID 40136647, 2025). "To evaluate the potential role of GATAD2B in promoting chemoresistance, we analyzed the expression of GATAD2B in breast cancer patients receiving chemotherapy." (PMID 40136647, 2025). "We for the first time showed that GATAD2B is critical for CSCs function in breast cancer and is regulated directly by OGT via O-GlcNAcylation." (PMID 40136647, 2025). "Together, these data suggest a critical role of GATAD2B in regulating breast cancer stem-like cells." (PMID 40136647, 2025). "ITCH knockdown increased the level of GATAD2B, but also elevated the mammosphere formation of breast cancer cells and increased cancer stem cell factors SOX2 and c-Myc." (PMID 40136647, 2025). "The expression of GATAD2B is critical and sufficient to maintain and promote CSCs phenotype of breast cancer cells." (PMID 40136647, 2025). "To further understand the mechanism of GATAD2B regulation by O-GlcNAcylation, we confirmed O-GlcNAcylation of GATAD2B was dynamically modulated by O-GlcNAc cycling enzymes in breast cancer cells." (PMID 40136647, 2025). "Together, these data indicate that GATAD2B plays a critical role in maintaining the cancer stem-like cells properties in multiple breast cancer cell lines." (PMID 40136647, 2025). "Genetic inhibition of ITCH enhances the stability of GATAD2B, mammosphere formation and expression of CSCs factors in breast cancer cells." (PMID 40136647, 2025). "Together, we identify a key role of GATAD2B and ITCH in regulating CSCs in breast cancer and GATAD2B O-GlcNAcylation as a mechanism regulating breast cancer stem-like populations and promoting chemoresistance." (PMID 40136647, 2025). "O-GlcNAcylation of GATAD2B at the C-terminus protects GATAD2B from ubiquitination and proteasomal degradation in breast cancer cells." (PMID 40136647, 2025). "In addition, our study shows that GATAD2B is highly upregulated in breast cancer cells and in patient samples." (PMID 40136647, 2025). "However, GATAD2B stood out as it was amplified or overexpressed in nearly 20% of human breast cancer samples." (PMID 40136647, 2025). "Moreover, we for the first time showed that O-GlcNAcylation within the C-terminus of GATAD2B is critical for GATAD2B stability, as well as for the CSCs properties of breast cancer cells." (PMID 40136647, 2025). "Importantly, breast cancer patients containing high expression of GATAD2B RNA and protein were associated with poor survival rates." (PMID 40136647, 2025).
breast carcinoma (continued). "Label free proteomic results showed an increase in the level of ITCH, an E3-ligase, co-immunoprecipitated in OMSi treatment when compared to DMSO or TMG treatment, suggesting that ITCH may ubiquitinate GATAD2B in breast cancer cells." (PMID 40136647, 2025). "In MDA-MB-231 cells, GATAD2B knockdown significantly reduced expression of cancer stem-like cells factors OCT4, SOX2, c-Myc and NANOG, at both protein and mRNA level, further implicating the role of GATAD2B in maintaining cancer stem-like cells phenotype in breast cancer cells." (PMID 40136647, 2025). "However, reducing GATAD2B levels in breast cancer cells significantly reduced the OGT-mediated increase in mammosphere formation in MDA-MB-231 and SUM159 cells." (PMID 40136647, 2025). "Together, these data suggests that OGT and O-GlcNAc protects GATAD2B from proteasome-dependent degradation mediated by the E3 ligase ITCH and also identifies ITCH as a regulator of breast cancer stem cell functions." (PMID 40136647, 2025). "Collectively, we showed a novel regulatory mechanism of GATAD2B by OGT, which is pivotal for CSCs maintenance and function in breast cancer." (PMID 40136647, 2025). "Here, we showed that genetic inhibition of ITCH increased expression of GATAD2B, SOX2 and MYC, as well as mammosphere formation and CSCs population detected by ALDEFLOUR in multiple breast cancer cell lines." (PMID 40136647, 2025). "Here, using a global proteomic analysis, we identified GATAD2B of the NuRD complex as a target of OGT and O-GlcNAc in breast cancer." (PMID 40136647, 2025). "The function of ITCH in regulating CSCs in breast cancer could be, in part, a result of ITCH regulation on GATAD2B stability." (PMID 40136647, 2025). "Similar results were also observed in breast cancer cells SUM159 and HCI-10, suggesting GATAD2B may play a role in regulating stemness." (PMID 40136647, 2025). "GATAD2B was detected among those enriched by sWGA and the intensity of enriched GATAD2B was elevated by TMG treatment, verifying that GATAD2B could be directly modified with O-GlcNAc in breast cancer cells." (PMID 40136647, 2025). "Here, we show for the first time that GATAD2B is critical in maintaining and promoting CSCs phenotypes while O-GlcNAcylation of GATAD2B enhances its stability and protects from ITCH-mediated proteasomal degradation and contributes to cancer stem cell functions in breast cancer cells." (PMID 40136647, 2025). "Collectively, these data suggests that O-GlcNAcylation of GATAD2B can regulate its ubiquitination and interaction with E3 ligase ITCH and thus contribute to O-GlcNAc-mediated regulation of cancer stem cell phenotypes and chemoresistance in breast cancer cells." (PMID 40136647, 2025). "However, the function of GATAD2B in breast cancer has not yet been explored." (PMID 40136647, 2025). "However, the role of GATAD2B in breast cancer has not yet been reported." (PMID 40136647, 2025). "Consistent with this idea, our results show that GATAD2B, but not GATAD2A, can regulate CSCs function in breast cancer further implicating a specific role of GATAD2B in CSCs." (PMID 40136647, 2025). "Altogether, this data indicates that GATAD2B, but not GATAD2A, regulates cancer stem-like cell populations and cancer stem cell factors in breast cancer cells." (PMID 40136647, 2025).
endometriosis (1 paper, 2021). The growth of functional endometrial tissue in anatomic sites outside the uterine body. "A similar GWAS study aiming at identifying gene of reproductive behaviour failed as well to be found in common as at risk for endometriosis, albeit GATAD2B and ESR1 were found as most likely causal and are indeed increased in expression in endometriosis lesions compared to the eutopic endometrium." (PMID 34298916, 2021).
epilepsy (1 paper, 2024). A brain disorder characterized by episodes of abnormally increased neuronal discharge resulting in transient episodes of sensory or motor neurological dysfunction, or psychic dysfunction. "Although there is a small increased frequency of epilepsy in missense carrying subjects, GAND subjects possessing LoF and missense GATAD2B variants typically present with similar phenotypes, indicating that haploinsufficiency models should be appropriate to model GAND." (PMID 38238293, 2024).
Kleefstra syndrome (1 paper, 2025). A genetic disorder characterized by intellectual disability, childhood hypotonia, severe expressive speech delay and a distinctive facial appearance with a spectrum of additional clinical features. "One study that compared the adaptive behaviours of several monogenic NDDs (Kleefstra syndrome, Koolen‐de Vries syndrome, and GATAD2B‐related syndrome, and a mixed group) advocated for syndrome‐specific adaptive and maladaptive functioning." (PMID 39846212, 2025).
lung adenocarcinoma (1 paper, 2018). A carcinoma that arises from the lung and is characterized by the presence of malignant glandular epithelial cells. "We identified three genes (GATAD2B, ACVR1B, and ZC3H11A) whose overexpression significantly correlates with mutant KRAS lung adenocarcinoma vs wild-type KRAS status in patients." (PMID 30013058, 2018). "Finally, consistent with the previous NSCLC dataset, GATAD2B copy-number driven expression (****p < 0.0001, t-test) was higher in KRAS mutant compared to wild type lung adenocarcinomas (n = 517 patients, Wilcoxon rank-sum, p < 0.0350)." (PMID 30013058, 2018).
Macrocephaly (1 paper, 2021). Occipitofrontal (head) circumference greater than 97th centile compared to appropriate, age matched, sex-matched normal standards. "Here, we report a 12-year-old boy with macrocephaly and ID with a novel GATAD2B missense variant." (PMID 33530161, 2021).
pancreatic ductal adenocarcinoma (1 paper, 2018). An infiltrating adenocarcinoma that arises from the epithelial cells of the pancreas. "Additional mining of TCGA genomics data revealed that GATAD2B is also commonly amplified in KRAS mutant cancers in other lineages, including pancreatic ductal adenocarcinoma, where KRAS is mutationally activated in greater than 90% of cases 4,9,29,30." (PMID 30013058, 2018).
Sifrim-Hitz-Weiss syndrome (1 paper, 2021). A rare multiple congenital anomalies/dysmorphic syndrome due to CHD4 gene mutations. "CHD4 mutations lead to Sifrim-Hitz-Weiss syndrome, while GATAD2B mutations lead to GATAD2B-associated neurodevelopmental disorder." (PMID 33946340, 2021).
triple-negative breast carcinoma (1 paper, 2025). An invasive breast carcinoma which is negative for expression of estrogen receptor (ER), progesterone receptor (PR), and human epidermal growth factor receptor 2 (HER2). "High expression of GATAD2B was observed at the protein level in both luminal and triple negative breast cancer (TNBC) patients." (PMID 40136647, 2025).